NRAS (NRAS proto-oncogene, GTPase)
Diseases named in the same sentence as NRAS in open-access papers (continued):
Sharing a sentence is not in itself a finding about the gene and the disease.
melanoma (continued). "Constitutively activated canonical WNT signaling via β-catenin has been shown to act synergistically with the MAPK pathway, by suppressing the expression of p16INK4A and cooperating with NRAS in the transformation of a melanocytic lesion into melanoma." (PMID 37762707, 2023). "A PLK inhibitor showed synergy with only one of two BRAF (upstream of MEK) inhibitors studied in a panel of melanoma cell lines, and demonstrated efficacy in a NRAS mutant melanoma." (PMID 37126527, 2023). "Previous studies have shown that MALAT1 is highly enriched in the nuclei of human cells, including NRAS mutant melanoma." (PMID 37235843, 2023). "This research seeks to provide critical insights into potential precision therapies for NRAS-mutant melanoma patients, ultimately advancing melanoma therapeutics and improving patient outcomes." (PMID 38067230, 2023). "BRAF/NRAS mutant melanoma cells activate the Nrf2 signaling pathway to protect cells against oxidative stress." (PMID 36747120, 2023). "In melanomas, this dysregulation is often caused by activating mutations in the BRAF and NRAS genes." (PMID 37235843, 2023). "The most common mutations in melanoma involve the MAPK signaling pathway, where acquired mutations in the genes encoding two kinases, BRAF and NRAS, result in continuous activation and aberrant cell proliferation." (PMID 37762707, 2023). "First-line therapy for patients with metastatic NRAS-mutant melanomas is immune checkpoint blockade; however, only a subset of patients respond (30–60%)." (PMID 36765910, 2023). "Acral melanomas harbor KIT, NRAS, and BRAF mutations, mucosal melanomas KIT and NRAS mutations, and uveal and melanomas arising in blue nevi uniquely have GNA11 and GNAQ mutations." (PMID 37841001, 2023). "In our study, we used a proteomic approach-based IMS technology to investigate melanoma tissues carrying BRAF and NRAS mutations." (PMID 36982192, 2023). "The correlation between MALAT1 and NRAS expression was high in both comparisons, and even higher in melanoma." (PMID 37235843, 2023). "In the phase 1 study of tunlametinib monotherapy for NRAS-mutant melanoma, tunlametinib demonstrated acceptable tolerability and substantial clinical activity as well as favorable PK profiles." (PMID 37808191, 2023). "Only serum CXCL10 levels exhibited significant differences across patients harboring melanomas with different mutations (BRAF, CDKN2A, NF, NRAS)." (PMID 37435077, 2023). "As already demonstrated by numerous authors, when extensive molecular tests were available, most of the tumors discussed in this review carry mutations typical for melanomas, such as NF1, BRAF, and NRAS mutations." (PMID 37373134, 2023). "NRAS mutant-mediated aggressiveness is not only limited to melanoma but its correlation with the higher mortality rate in pediatric AML is also observed." (PMID 37083947, 2023). "Anticipating the development of such resistance to a newly tested combination of CDK4/6i and MEKi, we characterised the transcriptomic responses in 3 NRAS mutant melanoma cell lines over an extended treatment duration of 33 days." (PMID 37420093, 2023). "Our exciting in vivo data have uncovered a potential new treatment for NRAS-driven melanomas, an understudied and highly aggressive subtype with notoriously poor outcomes." (PMID 36765910, 2023). "In a single NRAS mutant melanoma patient, this combination was found to be effective, perhaps related to CDKN2A mutation status." (PMID 37126527, 2023). "Although the role of p38 has been reported to be that of both tumor suppressor and oncogene, we show here that p38 specifically plays the role of a tumor suppressor in NRAS-mutant melanoma." (PMID 36765834, 2023). "It is infrequently mutated in acquired melanocytic nevi (<5%) but is the predominant mutated driver oncogene in congenital nevi; 95% of large congenital nevi are NRAS mutant, and these lesions have a higher propensity for melanoma transformation." (PMID 36834954, 2023).
melanoma (continued). "In contrast, while we showed that nilotinib treatment (24 h) induced RAF heterodimerization in MEKi-resistant NRAS-mutant melanoma cells, the result is inhibition of MEK/ERK and decreased coupling of NRAS and/or ERK to RAF rather than MEK/ERK activation." (PMID 36765910, 2023). "For instance, pan-RAF inhibitor LXH254 blocks dimeric BRAF and CRAF, which can provide a potential clinical strategy when combined with MEK or ERK inhibitors to treat KRAS mutant NSCLC or NRAS mutant melanoma." (PMID 38111008, 2023). "We showed that one such inhibitor prevents MEKi resistance from developing in a NRAS-mutant melanoma animal model." (PMID 36765910, 2023). "Other somatic mutations have also since been identified in melanomas including TERT, NRAS, NF1, and KIT in approximately 70-85%, 20-30%, 10-15, and 10% of melanomas, respectively." (PMID 37841001, 2023). "Both PHB ligands JI130 and MEL56 induce dose-dependent apoptosis in a panel of representative melanoma lines harboring wild-type BRAF and NRAS (HBL, LND1, and MM162), BRAF mutation (MM074 and MM029) or NRAS mutation (MM165)." (PMID 37508519, 2023). "Compared with more common BRAF-mutant melanomas (50–70% of cases), the understudied NRAS-mutant subtype (15–25% of cases) is more aggressive, and patients have a lower median overall survival." (PMID 36765910, 2023). "In line with our findings, a recent investigation used a combination of trametinib and chloroquine and observed an abrogation of PDA (pancreatic ductal carcinoma) as well as NRAS-mutant melanoma." (PMID 36765834, 2023). "In melanoma, many of the tumors which are BRAF wild-type carry activating mutations of NRAS, which encodes another component of the MAPK pathway positioned above RAF in the signaling cascade." (PMID 37219686, 2023). "Triple wildtype (TWT) melanomas that lack mutations in BRAF, NRAS, or NF1 form 10% of human melanomas and are heterogeneous in their genomic drivers." (PMID 36901951, 2023). "This real‐world study was conducted to assess the association of BRAF, NRAS, or KIT mutations with outcome in melanoma receiving adjuvant anti‐PD‐1 monotherapy." (PMID 37403699, 2023). "NRAS-mutant melanomas are a highly aggressive subtype and there is an unmet need to identify second-line treatment options for patients who fail to respond to immune-checkpoint blockade." (PMID 36765910, 2023). "Studies have also explored the relationship between TERT promoter mutations and other common genetic alterations in melanoma, such as BRAF and NRAS mutations." (PMID 37504268, 2023). "NF1 mutations are prevalent in melanomas that are wild-type for BRAF and NRAS, NF1 are considered driver mutations in these patients." (PMID 37762707, 2023). "Out of 462 melanoma samples, 322 (69.7%) were positive for Tier I/II variant and 8 patients had variants in two genes (5 patients with BRAF and NRAS; 3 patients with BRAF and KIT)." (PMID 37483495, 2023). "To investigate additional co-regulatory mechanisms of MALAT1 expression and MAPK signaling, we measured the response of MALAT1 expression to drug-induced MAPK inhibition in two NRAS-mutant melanoma cell lines, D04 and MM415." (PMID 37235843, 2023). "Using our transgenic zebrafish model as a platform for the identification of novel therapeutic targets, we discovered the role of p38 as a tumor suppressor in zebrafish as well as in patient-derived NRAS-mutant melanoma cultures." (PMID 36765834, 2023). "RAS has a high mutation rate in melanoma, and studies have found that the inactivation of RAS can lead to rapid death of tumor cells and tumor degeneration, and targeted inhibition of NRAS is also an effective treatment method." (PMID 35310910, 2022). "The long intergenic lncRNA MIRAT is upregulated following prolonged MAPK inhibition in NRAS mutant melanomas and modulates MAPK signaling by binding to the MEK scaffold protein IQGAP1." (PMID 35159386, 2022).
melanoma (continued). "Regarding EGFR-mediated control of tensile Rac1 activity, ERK/MAPK signalling has been implicated to drive the overexpression and activation of the Rac-GEF in BRAF- and NRAS-mutant melanoma, as well as in KRAS- and EGFR- mutant lung cancer." (PMID 36224221, 2022). "In general, melanoma can be classified into four subtypes based on the mutation carried in the tumour, i.e., BRAF, NRAS, NF1 or triple wild type." (PMID 35740696, 2022). "Almost 50% of all melanomas have a mutation in the BRAF gene, while 15–20% have a mutation in the NRAS gene, which leads to constitutive pathway activation." (PMID 36139698, 2022). "RAS consists of KRAS, NRAS and HRAS, and mutations in these genes have been frequently reported in colorectal cancer, pancreatic ductal adenocarcinoma, lung adenocarcinoma, melanoma and some hematological cancers." (PMID 36430761, 2022). "By using the same pooled melanoma and NSCLC cohorts, we also discovered other mutations of the genes FAT1, COL3A1, NRAS, NARS2, DCC, and PTPRT were associated with better ICI response and outcome." (PMID 35884556, 2022). "It has been proven that following the activation of the NRAS / BRAF pathway in melanoma, genes promoting cell proliferation such as SNAIL2 and ZEB2 are replaced by those regulating the migration such as ZEB1 and TWIST1." (PMID 35820816, 2022). "Other studies have also demonstrated the diagnostic utility of CSF ctDNA analysis, with mutation profiles generally consistent with the primary tumour type (e.g., NRAS and BRAF mutations from melanoma patients and EGFR mutations for lung BrM patients)." (PMID 35225863, 2022). "Expression of a stabilized mutated bcat in melanocytes, along with a mutated human NRAS oncogene, constitutively activating the MAPK pathway (Tyr::NRASQ61K/°; Tyr::bcat-mut/°) led to accelerated onset and increased the number of melanomas in a mouse model." (PMID 35158973, 2022). "The combinations of LXH254 and trametinib or the ERK inhibitor, LTT462, are currently in evaluation in patients with previously treated BRAF V600 or NRAS mutant melanoma (NCT04417621)." (PMID 35053435, 2022). "At present, the treatment of NRAS mutant melanoma mainly focuses on the inhibition of the NRAS signal pathway-related kinase protein." (PMID 36551302, 2022). "As CCT196969 has been suggested as a potential second line treatment for BRAF inhibitor resistant melanoma and first line therapy for NRAS- and BRAF-mutated melanoma, combination therapy with PI3K inhibitors should be investigated in the future." (PMID 36084109, 2022). "In murine melanoma models of BRAF and NRAS mutant melanoma, high TMB increases MAPK inhibitor response durability in a CD8 + T cell dependent manner." (PMID 36058945, 2022). "Understanding how NRAS-driven melanomas develop therapy resistance is crucial to develop new effective therapeutic strategies for patients with this kind of melanoma." (PMID 36551302, 2022). "MIRAT, a novel cytoplasmic intergenic lncRNA, is upregulated in NRAS mutant melanoma and regulates the MEK scaffold protein IQGAP1 and MAPK signaling pathways to influence the drug resistance of tumor cells." (PMID 36601121, 2022). "Bioinformatic analyses of melanoma gene expression datasets revealed different subsets of BRAF/NRAS melanomas that differ in the endogenous expression of MITF independently of the oncodriver mutation." (PMID 35580987, 2022). "Studies have found that 70% of melanomas are associated with BRAF and NRAS gene mutations, so there are many studies on BRAF- and NRAS-mutant melanoma." (PMID 35310910, 2022). "The main melanoma driving mutations are part of ERK pathway, with BRAF mutations being the most frequent ones, followed by NRAS, NF1 and MEK mutations." (PMID 35941108, 2022). "Transcriptome sequencing analysis of tissue samples from melanoma patients indicated that mutations closely related to melanoma progression mainly included BRAF mutation, NRAS mutation and NF1 mutation." (PMID 36601121, 2022).
melanoma (continued). "Lastly, in another phase I trial with 29 patients, trametinib and hydroxychloroquine (an autophagy inhibitor) in NRAS-mutant melanoma and neuroblastoma are being investigated." (PMID 35954441, 2022). "Among all genes analyzed, DUSP4 appeared to have a major role in controlling the viability of BRAF- and NRAS-mutant melanoma cells." (PMID 35580987, 2022). "Mutations in the NF1 gene leading to the inactivation of the encoded protein occur in melanoma with a frequency of 12–30% and are the third most frequent mutation in melanoma (after BRAF and NRAS)." (PMID 35565444, 2022). "Here we observed that NRAS expression was dramatically elevated in melanomas containing a relatively weak driver, NRAS61H." (PMID 35672316, 2022). "Targeting nodes of the CD133, AKT, or BCL-2 survival pathways with trametinib highlights the potential for combination therapies for NRAS-mutant melanoma stem cells for the development of more effective treatments for patients with high-risk melanoma." (PMID 35216449, 2022). "In a phase Ib/II, open-label clinical trial, 102 patients with locally advanced or metastatic NRAS-mutant melanoma were treated with a MEK inhibitor (binimetinib), and a CDK4/6 inhibitor (ribociclib)." (PMID 35954441, 2022). "Related experiments are executed in NRAS‐mutant melanoma and solid tumors (NCT04835805 and NCT03284502)." (PMID 36254250, 2022). "NRAS mutations and BRAF amplification are also often identified in genetic analysis of melanoma samples." (PMID 35565444, 2022). "In contrast, melanomas with WT BRAF, NRAS and NF1 that are driven by activating KIT mutations can be treated with the RTK inhibitor imatinib, yielding response rates of 16–30%; however, most of these responses were partial and transient." (PMID 35234863, 2022). "STK19 targeted inhibitors was effective in blocking the oncogenic NRAS-driven malignant transformation of melanocytes and melanoma growth in vitro and in vivo." (PMID 36551302, 2022). "The selection of new NRAS mutations is the principal cause of melanoma reactivation in BRAF- or NRAS-mutant cases, explaining why BRAF-mutant or NRAS-mutant melanomas exhibit the largest resistance to B-Raf inhibitors." (PMID 36143375, 2022). "Crossing these alleles to a melanocyte-specific Cre, we find that the melanomagenic potential of NRAS mutants parallels their frequency in human melanoma." (PMID 35672316, 2022). "The objective of this study was to determine the pharmacokinetics (PK) of tunlametinib and its main metabolite M8 in patients with NRAS-mutant melanoma following a single dose and multiple doses in a phase I safety and PK study." (PMID 36386136, 2022). "The reported median progression-free survival under binimetinib treatment was 2.8 months compared to 1.5 months under standard chemotherapy in patients with NRAS-mutant melanoma." (PMID 35234863, 2022). "The ArcherDX custom melanoma ctDNA panel detected 13/17 (76%) patients with BRAF- or NRAS-mutant melanoma." (PMID 35494035, 2022). "In this study, we investigated the effect of inhibition of Axl expression on the targeted inhibition of the PI3K/Akt pathway in NRAS-mutant melanoma cells." (PMID 35310910, 2022). "Mutations are frequently seen in the NRAS proto-oncogene (NRAS; 28%) and BRAF (52%) genes, and 80% of BRAF-mutated melanomas display the BRAFV600E mutation." (PMID 36084109, 2022). "It is noteworthy that more than half of the melanomas evidence BRAF V600 mutations with ∼25% of neuroblastoma RAS viral oncogene homolog (NRAS) gene mutations." (PMID 35360535, 2022). "In a larger cohort, however, patients with NRAS-mutant tumors showed comparable rates of response to immunotherapy but significantly shorter overall survival compared to patients with NRAS-WT melanoma." (PMID 35234863, 2022). "Cai and his colleagues found that PDPK1i+MEKi is an effective immunostimulatory approach counter to NRAS mutant melanoma." (PMID 36551688, 2022).
melanoma (continued). "Here, the authors show that under metabolic stress NRAS-mutant melanoma cells activate a BRAF-dependent glycolysis pathway for survival, leading to improve efficacy of sorafenib when combined with glycolysis inhibitors." (PMID 36402789, 2022). "The input for the app includes two drop-down menus of treatments and radio buttons to choose the (sub-) group of patients corresponding to the major melanoma genotypes (All, NRAS, BRAF, Triple WT)." (PMID 36139469, 2022). "The pathogenesis of malignant melanomas is very complex, including a series of complicated interactions among external events and endogenous triggers, genetic mutations of BRAF, NRAS, and KIT, as well as endogenous and immune-related factors of the tumor." (PMID 35220953, 2022). "A preclinical study showed that simultaneous inhibition of both MEK, which is downstream of Ras, and CDK4/6, can induce tumor regression in NRAS-mutant melanoma." (PMID 35954441, 2022). "BRAF and NRAS cooperate with Rho-ROCK for transformation, and as such BRAF- and NRAS-mutant melanomas harbour amoeboid characteristics." (PMID 36699013, 2022). "The activation of the MAPK pathway in NRASmut melanoma is achieved through the activation of the NRAS effector CRAF." (PMID 36551302, 2022). "We also analysed cfRNA copies of KPNA2, DTL, BACE2 and DTYMK across different mutational genotypes of melanoma tissue (N = 33 BRAF/NRAS wild‐type, of those N = 4 positive for TERTprom; N = 41 BRAFV600 mutant and N = 25 NRASQ61 mutant melanomas)." (PMID 36320118, 2022). "Genetic alterations of either NRAS (15–20%) or BRAF (40–50%) arise early during melanoma pathogenesis and are preserved throughout tumor progression." (PMID 35580987, 2022). "We demonstrated that HSPB8 regulates the levels of the active prenylated form of NRAS in NRAS-mutant and NRAS-wild-type melanoma cell lines." (PMID 36400750, 2022). "BRAF-mutant melanomas are prevalent in body areas of intermittent sun exposure, while NRAS-mutant melanomas are mainly observed in chronic sun-damaged areas." (PMID 35804995, 2022). "In human NRAS-mutant melanoma xenograft models, upregulation of serine biosynthesis and expression of PHGDH are responsible for the resistance to MAPK kinase inhibitors." (PMID 35011702, 2022). "We explored this question in a suite of eight GEMMs and discovered a direct correlation between the frequency of a particular NRAS mutant in human melanoma and its melanomagenic potential in mice." (PMID 35672316, 2022). "Our studies then focused on melanoma cells carrying the Q61R NRAS mutation (BLM cells) or the V600E BRAF mutation (A375 cells), representing the main mutations identified in melanoma patients." (PMID 36400750, 2022). "As our data show that DUSP4 depletion leads to cell death through MITF suppression, we evaluated the sensitivity of BRAF/NRAS–mutant melanoma cells expressing either high or low levels of MITF to DUSP4 knockdown." (PMID 35580987, 2022). "We selected some BRAF- and NRAS-mutated cell lines such as SkMel28, A375 and Mel Juso to study the role of UBIAD1 in the antioxidant defense of melanoma." (PMID 35255427, 2022). "Along with the allelic series of conditional mouse models we describe, these results establish a mechanistic basis for the enrichment of specific NRAS mutants in human melanoma." (PMID 35672316, 2022). "In another study on NRAS-mutant melanoma, genome-wide CRISPR/Cas9 screens were used to identify genes involved in resistance to trametinib, which is a MEK1/2 inhibitor." (PMID 35715750, 2022). "We found that HSPB8 regulates RAS-prenylation both in NRAS-mutant and NRAS-wild-type melanoma cell lines, inhibiting the Akt/mTOR molecular pathway." (PMID 36400750, 2022).